DPP4 (dipeptidyl peptidase 4)
Diseases named in the same sentence as DPP4 in open-access papers (continued):
Sharing a sentence is not in itself a finding about the gene and the disease.
peripheral artery disease (8 papers, 2018 to 2026). "Furthermore, in another retrospective cohort study, each of the 11,431 T2DM patients with peripheral artery disease (PAD) taking the SGLT2 inhibitor or DPP-4 inhibitor were analyzed for the risk for ischemic stroke and acute MI after propensity score matching." (PMID 35011882, 2021).
renal carcinoma (8 papers, 2009 to 2024). A carcinoma arising from the epithelium of the renal parenchyma or the renal pelvis. "Taking into consideration the tumor-promoting MSCs effects in RCC, the results of our study suggest that DPP4 loss may contribute to the progression of renal cancer." (PMID 37563650, 2023). "Recent studies revealed that other SARS-CoV-2 factors such as ANPEP (alanyl aminopeptidase, membrane), ENPEP (glutamyl aminopeptidase), and DPP4 (dipeptidyl peptidase 4) are expressed at high levels in renal cancer, especially in ccRCC." (PMID 38255667, 2023). "This could suggest that renal cancer may have been an inducer of TMA-like lesions under DPP4-inhibitor treatment." (PMID 39135967, 2024). "We should not conclude from this single case report that DPP4-inhibitors are associated with TMA-like lesions or renal cancer." (PMID 39135967, 2024). "The reports on the role of DPP4 in renal cancer provided contradicting results." (PMID 37563650, 2023). "Further analysis of renal carcinoma subtypes revealed that KIRP and KIRC tumors exhibit increased levels of DPP4, ANPEP, and ENPEP along with ACE2 receptors." (PMID 33330620, 2020). "We further analyzed the expression of ACE2, ANPEP, ENPEP, DPP4, and TMPRSS2 gene in renal carcinoma tissues." (PMID 33330620, 2020). "They did not discuss renal lesions, but DPP4 inhibitors and renal cancer may be considered in the future." (PMID 39135967, 2024). "Analysis of different tumor stages of renal carcinoma subtypes revealed a statistically significant (p < 0.01) negative Spearman's correlation of ACE2 and DPP4 with increasing stages of KIRC and KIRP tumors." (PMID 33330620, 2020).
urothelial carcinoma (8 papers, 2017 to 2024). A malignant neoplasm derived from the transitional epithelium of the urinary tract (urinary bladder, ureter, urethra, or renal pelvis). "Overexpression of DPP4 in urothelial carcinoma correlates with tumor cell growth, proliferation, and enhanced cell migration and invasion." (PMID 32498358, 2020). "Further research to elucidate the mechanism of DPP4 contributed to the malignant behavior in urothelial carcinoma and the effectiveness of DPP4 inhibitors as targeted therapy are warranted." (PMID 27936466, 2017). "Suppression of DPP4 attenuates aggressiveness and promotes apoptosis in urothelial carcinoma cells." (PMID 32498358, 2020). "By mining the datasets obtained from the Gene Expression Omnibus (GEO, NCBI, Bethesda, MD, USA) and focused on the proteolysis pathway, we discovered that the transcription of dipeptidyl peptidase 4 (DPP4) was significantly upregulated in advanced-stage human urothelial carcinomas." (PMID 27936466, 2017). "Also, DPP4 is an independent prognosticatory biomarker in urothelial carcinoma." (PMID 27936466, 2017).
acute myeloid leukemia (7 papers, 2018 to 2025). Acute myeloid leukemia (AML) is a group of neoplasms arising from precursor cells committed to the myeloid cell-line differentiation. "We discovered that DPP4 is a highly upregulated gene during early progression of acute myeloid leukemia and that it marks a more proliferative subpopulation that is confined to specific bone marrow microenvironments." (PMID 36424441, 2022).
Arrhythmia (7 papers, 2015 to 2025). Any cardiac rhythm other than the normal sinus rhythm. "Given the elevated arrhythmia risk in DM1 patients, it is crucial to assess and monitor cardiac function when using DPP-4 inhibitors." (PMID 41018201, 2025). "In this context, we examined AP activity involved in adenosine metabolism and purinergic signaling in arterial capillaries, as well as DPP-4 activity in venous capillaries, which is known to be involved in collagen metabolism and arrhythmias." (PMID 39766216, 2024). "Our results suggest the pleiotropic effects of DPP-4 inhibition and suggest a potential role for these agents in anti-arrhythmia." (PMID 26811539, 2016). "Thus, the DPP-4 inhibitors may have important biological effects that prevent the occurrence of post-infarcted arrhythmias." (PMID 25388908, 2015).
cerebrovascular disease (7 papers, 2021 to 2025). "Factors such as living in an urban region, a history of DM, HTN, cardiovascular disease, and cerebrovascular disease, as well as the use of aspirin, DPP-4 inhibitors, metformin, and sulfonylureas, were associated with better PFS." (PMID 38254739, 2024). "Accordingly, we hypothesized that DPP-4 inhibitors yield a beneficial effect on cardiovascular and cerebrovascular diseases." (PMID 35615279, 2022). "Hence, the DPP4 inhibitor is a conceivable consideration for therapy of neurodegenerative diseases and cerebrovascular diseases." (PMID 34489872, 2021). "Therefore, we still believe that DPP-4 inhibitors might contribute to the suppression of the occurrence and progression of cardio-cerebrovascular disorders." (PMID 40771927, 2025).
chronic heart failure (7 papers, 2007 to 2024). "Long-term treatment with the DPP-4 inhibitor vildagliptin, started immediate or late after MI, does not preserve cardiac function in a rat post-MI remodeling model of chronic heart failure despite increases in plasma active GLP-1 levels by inhibiting DPP-4 activity." (PMID 21955567, 2011). "The “ESC Guidelines for the diagnosis and treatment of acute and chronic heart failure” commented that in patients with HF the treatment of choice should be metformin, especially because no CV data were available for DPP-4 inhibitors and GLP-1 RAs." (PMID 29020969, 2017).
clear cell renal cell carcinoma (7 papers, 2011 to 2024). "DPP-4 was implicated in the development of thyroid neoplasia, such as papillary and follicular cancer, and associated with decreased survival of patient with clear cell renal carcinoma." (PMID 26290759, 2015). "Histone methyltransferase SUV39H1 catalyzes H3K9me3 on the DPP4 promoter, thereby repressing its expression and DPP4–NOX1 complex formation, ultimately inhibiting lipid peroxidation and ferroptosis in clear cell renal carcinoma." (PMID 39568772, 2024). "Expressions of CRAs, CD44, DPP4, GOT1 and HMGCR were significantly increased in renal clear cell carcinoma compared with those in normal kidney tissue." (PMID 33996565, 2021).
end-stage renal disease (7 papers, 2015 to 2025). "Alogliptin, a DPP4 inhibitor, was started, and the decline in renal function progressed to Cre 7.5 mg/dL; hemodialysis was initiated for end-stage renal failure." (PMID 39135967, 2024).
endometrial cancer (7 papers, 2017 to 2025). Primary or metastatic malignant neoplasm involving the endometrium (mucous membrane that lines the endometrial cavity). "In endometrial carcinoma, there is an inverse correlation between DPP4 expression and tumor grading." (PMID 27936466, 2017).
glioblastoma (7 papers, 2019 to 2025). The most malignant astrocytic tumor (WHO grade IV). "Cell adhesion signatures, such as integrin β1 and dipeptidyl peptidase-4 (DPP-4), which are expressed at high levels in murine and human M-MDSCs, act as regulators for tumor-promoting functions of M-MDSCs in glioblastoma." (PMID 37443711, 2023). "Remarkably, the important role of DPP4 in anti-tumor immunity has been revealed in many cancers including glioblastomas." (PMID 31097021, 2019). "While considering glioblastoma, we found SOX2, DUSP6, SLC24A3, KCNIP3, and DPP4 to be differentially the most upregulated, which have previously been found to be effective in glioblastoma formation and prognosis." (PMID 38769480, 2024). "In fact, the BS149 cell line generated from recurrent glioblastoma is more malignant than the other four glioblastoma cell lines (LN018, LN215, LN229, and LN319) and has higher mRNA levels of DPP4, ANPEP, and ENPEP, further corroborating the potential oncogenic roles of ANPEP and ENPEP in GBM." (PMID 35464443, 2022).
Impaired glucose tolerance (7 papers, 2014 to 2022). An abnormal resistance to glucose, i.e., a reduction in the ability to maintain glucose levels in the blood stream within normal limits following oral or intravenous administration of glucose. "Moreover, as DPP4 negatively impacts β cell function, the relationship between high sDPP4 levels and the presence of impaired glucose tolerance and T2DM is almost self-explanatory." (PMID 36140405, 2022). "Recently, a 3-month clinical trial of vildagliptin, another oral DPP-4 inhibitor, revealed that this agent improved oral glucose tolerance test outcomes and modestly improved hemoglobin A1c in kidney transplant recipients with impaired glucose tolerance (IGT)." (PMID 24817885, 2014). "After in vitro experiments were conducted to investigate the DPP-4 inhibition ability and receptor affinity of GLP-1RAs, further in vivo experiments were conducted to compare the hypoglycemic effects of GLP-1RAs on impaired glucose tolerance (IGT) mice." (PMID 35745659, 2022). "In our study, no improvement of impaired glucose tolerance was observed with siRNA treatment in line with some but not all previously published studies in obese DIO mice using different means to reduce hepatic dpp4 expression." (PMID 31794591, 2019). "This study aimed to elucidate whether a dipeptidyl peptidase 4 inhibitor could reduce the glycemic excursion and stabilize the coronary plaques compared with conventional management in coronary artery disease (CAD) patients with impaired glucose tolerance (IGT)." (PMID 33588758, 2021).
malignant pleural mesothelioma (7 papers, 2017 to 2025). A malignant neoplasm that arises from mesothelial cells in the pleura and shows a diffuse growth pattern. "For example, Okamoto T and colleagues found that DPP4 knockdown significantly inhibited the proliferation of malignant pleural mesothelioma." (PMID 37907650, 2023). "Overexpression of DPP4 also prolonged the survival of the patient with malignant pleural mesothelioma." (PMID 27936466, 2017). "In addition, an interaction between SST4 and the membrane glycoprotein dipeptidyl peptidase-4/cluster of differentiation 26 (CD26) occurs in malignant pleural mesothelioma cells." (PMID 30232095, 2018).
unstable angina (7 papers, 2016 to 2025). "Extended outcome combinations of MACE, adding unstable angina and HHF, respectively, did not change the lower risk associations with dapagliflozin compared with DPP‐4 inhibitors." (PMID 28771923, 2018). "In addition, there was no different effect between GLP-1 agonists and DPP-4 inhibitors on angina events (OR: 1.43, 95% CrI: 0.46–4.7)." (PMID 29150631, 2017).
anaplastic large cell lymphoma (6 papers, 2003 to 2021). Anaplastic large cell lymphoma (ALCL) is a rare and aggressive peripheral T-cell non-Hodgkin lymphoma, belonging to the group of CD30-positive lymphoproliferative disorders, which affects lymph nodes and extranodal sites. "At the functional level, antibody- or siRNA-mediated inhibition of CD26/DPP4 in the CD26+ T-ALCL (anaplastic large cell lymphoma) line Karpas-299 resulted in decreased adhesion properties in vitro and improved survival in vivo." (PMID 34885056, 2021).
bladder cancer (6 papers, 2018 to 2025). "We found that four tumor types with the highest DPP4 expression presented with a decreased level of DPP4 DNA methylation, including prostate adenocarcinoma, thymoma, bladder cancer, and KIRC." (PMID 33614513, 2021).
diabetic ketoacidosis (6 papers, 2021 to 2025). The metabolic condition resulted from uncontrolled diabetes mellitus, in which the shift of acid-base status of the body toward the acid side because of loss of base or retention of acids other than carbonic acid is accompanied by the accumulation of ketone bodies in body tissues and fluids. "Clinical trials have reported a higher incidence of diabetic ketoacidosis (DKA) among patients using SGLT2 inhibitors, including dapagliflozin, than in those using dipeptidyl-peptidase IV (DPP-4) drugs." (PMID 40909034, 2025). "The incidence rate of diabetic ketoacidosis (DKA) were 1.4 and 0.6 events per 1000 person years among SGLT-2i and DPP-4 inhibitors users, hazard ratios comparing SGLT-2i with DPP-4i was 2.14 (1.17–4.09)." (PMID 33606705, 2021).
Hypercholesterolemia (6 papers, 2018 to 2022). An increased concentration of cholesterol in the blood. "DPP-4 inhibitor users, compared to DPP-4 inhibitor nonusers, had less hypercholesterolemia and LDL but higher serum creatinine." (PMID 36422091, 2022).
liver dysfunction (6 papers, 2015 to 2025). "The reduction in transaminase levels observed in our SGLT2 add-on group may demonstrate the difference between the effects of SGLT2 and DPP4 inhibitors in improving liver dysfunction." (PMID 39114607, 2024). "In addition, dipeptidyl peptidase-4 (DPPIV) enzyme was mistrafficked and the liver bile canaliculi lacked branching, highlighting the importance ofMYO5B in studying liver dysfunction associated with MVID patients." (PMID 31824659, 2019).
mycosis fungoides (6 papers, 2003 to 2025). Classical mycosis fungoides is the most common type of mycosis fungoides (MF), a form of cutaneous T-cell lymphoma, and is characterized by slow progression from patches to more infiltrated plaques and eventually to tumors. "In cutaneous T-cell lymphoma, especially in Sézary syndrome and in mycosis fungoides, CD26/DPP4 expression patterns emerged as an established marker for diagnosis and treatment monitoring." (PMID 34885056, 2021). "Moreover, the loss of CD26 expression in the disease progression of cutaneous T cell lymphoma (CTCL) and its most frequent forms, mycosis fungoides (MF) and Sézary syndrome (SS), correlated with lower serum CD26/DPP4 levels." (PMID 39001488, 2024). "Nevertheless, numerous studies analyzed CD26/DPP4 cell surface expression and levels of sCD26/DPP4 in the serum of patients with cutaneous T-cell lymphoma (CTCL) including the most frequent CTCL mycosis fungoides (MF) and Sézary syndrome (SS)." (PMID 34885056, 2021).
non-small cell lung carcinoma (6 papers, 2015 to 2026). A group of at least three distinct histological types of lung cancer, including non-small cell squamous cell carcinoma, adenocarcinoma, and large cell carcinoma. "DPP-4 inhibitors may also be promising in combination therapies for non-small cell lung cancer (NSCLC)." (PMID 40282969, 2025).
Pemphigoid (6 papers, 2019 to 2025). "Drug-induced pemphigoid is also known, and has recently attracted particular attention in relation to dipeptidyl peptidase-4 (DPP-4) inhibitors and immune checkpoint inhibitors." (PMID 37189450, 2023). "In an enzyme-dependent role, the accumulation of CXCL12, a substrate of DPP-4, may be involved not only in the pathogenesis of pemphigoid but also in renal disease." (PMID 38055184, 2024).
polycystic ovary syndrome (6 papers, 2020 to 2025). A disorder that manifests as multiple cysts on the ovaries. "DPP4 serum activity is elevated in patients with polycystic ovary syndrome, DPP4 serum levels are closely related to anti-Müllerian hormone (AMH) serum levels, and the use of DPP4 inhibitors may improve IR." (PMID 34956381, 2021).
pulmonary hypertension (6 papers, 2019 to 2026). Increased pressure within the pulmonary circulation due to lung or heart disorder. "DPP4 inhibitor probably exerted its role in pulmonary hypertension by promoting vasodilatation of the pulmonary artery and producing anti-inflammatory effects." (PMID 34955820, 2021). "Thus, DPP4 inhibition might be a potential therapeutic target for pulmonary hypertension, and clinical trials are needed." (PMID 34955820, 2021). "DPP4 was found to be highly expressed in pulmonary arterial SMCs, and the Akt/mTORC1 and NF-κB pathways were demonstrated to mediate the development of pulmonary arterial SMC and hypoxia-induced pulmonary hypertension." (PMID 34955820, 2021). "Furthermore, recent studies have reported that CD26/DPP4 contributed to non-typeable H. influenzae-induced lung inflammation in COPD, and can participate in the pathogenesis of pulmonary hypertension." (PMID 34944016, 2021).
respiratory infections (6 papers, 2018 to 2026). "We found that the risk of respiratory infections was lower when DPP-4 inhibitor therapy was used concomitantly with insulin, relative to the metformin + insulin combination regimen in male T2DM patients (adjusted OR 0.77; 95% CI 0.61–0.98, p = 0.04)." (PMID 37891260, 2023). "When pooling the estimated effects from previous studies and ours, the overall risk of respiratory infections linked to DPP-4 inhibitors is still inconclusive." (PMID 37891260, 2023). "In an early meta-analysis, DPP4 inhibitors were reported to increase the risk of upper respiratory infection and UTI24." (PMID 29535389, 2018). "Collectively, our studies demonstrate that DPP4, a specific factor upregulated during cellular senescence, can influence barrier function and respiratory infections." (PMID 37728586, 2024). "Further studies are required to confirm whether DPP-4 inhibitors would exert clinically significant protective effects against respiratory infections." (PMID 37891260, 2023). "In our analysis, we did not detect high levels of co-expression of ACE2 and DPP4 in human lung tissue; however, both SARS-CoV-2 and MERS-CoV cause respiratory infections and associated disease symptoms in humans." (PMID 32902372, 2020). "In our analysis, we did not detect high levels of co-expression of ACE2 and DPP4 in human lung tissue; however, both SARS-CoV-2 and MERS-CoV cause respiratory infections in humans." (PMID 32902372, 2020).
SARS-CoV infection (6 papers, 2014 to 2023). "Further evaluation is needed to determine whether downregulation of CD26/DPP4 is a general hallmark of persistent MERS-CoV infection in animal models of MERS and whether the receptor influences pathogenesis in a manner similar to that seen with ACE2 downregulation in persistent SARS-CoV infection." (PMID 25409519, 2014).
T-cell leukemia (6 papers, 2009 to 2023). A malignant disease of the T-lymphocytes in the bone marrow, thymus, and/or blood. "Anti-CD26/DPP4 monoclonal antibodies (2F9, 1F7, and YS110) blocked the interaction between the S protein and CD26/DPP4, thereby neutralizing MERS-CoV infectivity in Huh-7 and JKT/CD26 (human T cell leukemia expressing human DPP4) cells." (PMID 34239932, 2021).
acute respiratory distress syndrome (5 papers, 2021 to 2026). Progressive and life-threatening pulmonary distress in the absence of an underlying pulmonary condition, usually following major trauma or surgery. "A higher risk of in-hospital death, intensive care unit (ICU) admission, and progression to acute respiratory distress syndrome (ARDS) was found to be linked with the use of DPP4 inhibitors for the chronic management of type 2 diabetes." (PMID 39727640, 2024). "Second, DPP-4 inhibitors (DPP-4I) suppress systemic inflammation, and diminish tissue damage in a mouse model of lipopolysaccharide (LPS)-induced Acute Respiratory Distress Syndrome (ARDS)." (PMID 34222054, 2021).